MPO (myeloperoxidase)
Diseases named in the same sentence as MPO in open-access papers (continued):
Sharing a sentence is not in itself a finding about the gene and the disease.
colitis (continued). "Treatment with Mutaflor tended to reduce the colitis-evoked increase in myeloperoxidase activity in the colonic mucosa, but this effect was statistically insignificant." (PMID 27433160, 2016). "NAC was able to restore both H2O2 and MDA to levels equal to the control group and decreased MPO levels versus the mild Colitis group (p < 0.05), thereby confirming its higher antioxidant power relative to LA." (PMID 27957238, 2016). "As expected, MPO activity is increased in different experimental models of colitis induced by TNBS, DSS and T cell transfer." (PMID 27070642, 2016). "In contrast, administration of rifaximin resulted in a significant reduction in mucosal activity of myeloperoxidase in rats with colitis." (PMID 27433160, 2016). "After the next 7 days mucosal activity of MPO in colon of rats with colitis was still significantly increased above a level observed in control rats without induction of colitis." (PMID 26798415, 2016). "Pro-inflammatory cytokines (TNF-α, IL-1β, and IL-6) levels and MPO activity from colitis rat colon tissue were significantly increased compared to those in sham group." (PMID 27303297, 2016). "Intragastric administration of L. lactis MG1363 FnBPA+ (pValac::dts::IL-4) was able to decrease the severity of colitis, with animals showing decreased levels of IL-12, IL-6 and MPO activity; and increased levels of IL-4 and IL-10." (PMID 27576902, 2016). "The next interesting finding originated from our present study is the influence of intraperitoneal administration of obestatin on the concentration of interleukin-1β (IL-1β) and myeloperoxidase activity in colonic mucosa of animals with colitis." (PMID 26798415, 2016). "According to these authors, NAC (150 mg·kg·d−1 for 45 days) decreased colitis symptoms, inflammation, cell apoptosis, and MPO and •NO levels." (PMID 27957238, 2016). "In rats with colitis, administration of ghrelin resulted in a statistically significant inhibition the colitis-evoked increase in myeloperoxidase activity in colonic mucosa." (PMID 27598133, 2016). "CBD BDS, both when given intraperitoneally and by oral gavage, decreased the extent of the damage (as revealed by the decrease in the colon weight/length ratio and myeloperoxidase activity) in the DNBS model of colitis." (PMID 27757083, 2016). "MPO is an index of neutrophil recruitment in the DSS-induced colitis model and in consequence reflects the inflammatory events in parallel with cytokine concentrations." (PMID 27847525, 2016). "In fact, most flavonoids assayed in experimental colitis models exhibited a significant reduction of colonic myeloperoxidase." (PMID 27070642, 2016). "While injected twice with 50 μg rSjcystatin after colitis, mice showed a significantly lower levels of MPO (0.59 ± 0.23) U/g, MAO (4.71 ± 1.11), MIO (3.50 ± 0.55), DAI (4.80 ± 0.84) and less colon shrinkage than the untreated colitis mice." (PMID 26728323, 2016). "The degree of colitis was assessed macro- and microscopically and tissue myeloperoxidase activity was determined." (PMID 27418880, 2016). "Administration of rifaximin after induction of colitis has decreased the activity of MPO and reduced concentration of IL-1β and TNF-α in colonic mucosa, reflecting the reduction in the local inflammatory reaction." (PMID 27433160, 2016). "Seven days after the induction of colitis, a three-fold increase in myeloperoxidase activity was observed in colonic mucosa as compared to that observed in animals without induction of colitis." (PMID 27598133, 2016). "Seven days after induction of colitis, in rats treated with ghrelin, mucosal activity of myeloperoxidase in the colon was reduced by around 36% when compared to rats with colitis without treatment with ghrelin." (PMID 27598133, 2016). "Maximal reduction of the colitis-induced increase in mucosal myeloperoxidase activity as observed after treatment with combination of rifaximin and Mutaflor." (PMID 27433160, 2016).
colitis (continued). "Acer3−/− mice that survived DSS treatment showed more severe colitis, as evidenced by a greater colon shortening, higher levels of inflammatory cytokines (Il-1β, Il-6, Il-23a and Tnf-α), higher MPO activity and more severe pathological manifestations." (PMID 26938296, 2016). "Regarding MPO levels, ulcer severity and area as well as the total colitis index, same results indicating meaningful alleviation of colitis was achieved after treatment with oral extract and essential oil." (PMID 27222834, 2016). "MPO+ neutrophils (CD11b+Ly6G+) infiltrated into the submucosal and mucosal areas of the colon in colitis-induced WT mice and Dcir1−/− mice (arrowheads)." (PMID 26497661, 2015). "We showed that CGA displayed a significant anti-inflammatory activity in a well-established mouse model of experimental colitis, as evidenced by reduction of macroscopic damage score, MPO activity, and inhibition of NF-κB activation." (PMID 25743575, 2015). "Although we observed the normal migration of bone marrow Dcir1−/− neutrophils toward MIP-2, we found reduced accumulation of MPO+ neutrophils in colons on day 5 of DSS colitis." (PMID 26497661, 2015). "Concerning other studies, our data showed that the TNBS induced an acute colitis in BALB/c mice characterized by intense weight loss, clinical score, macroscopic signs, MPO activity, tissue injury and invasion of inflammatory cells infiltration." (PMID 25853847, 2015). "In this model, we confirmed the resolution of TNBS-colitis by colonoscopic, macroscopic and microscopic evaluation of the colonic tissue, in addition to MPO activity." (PMID 25885345, 2015). "Experimental colitis was quantified in the rat model, macroscopically and by measuring the activity of tissue MPO and iNOS and levels of TNFα and IL-1β." (PMID 25949237, 2015). "The CTX administration resulted in decreased weight loss, disease activity index (DAI), macroscopic tissue damage, histopathological score and myeloperoxidase (MPO) activity analyzed after 4 days of acute TNBS colitis." (PMID 25853847, 2015). "In the intestine of Dcir1−/− mice with colitis, the number of tissue-injuring MPO+ neutrophils was lower than in WT mice, possibly because of the down-regulation of MIP-2 chemokine." (PMID 26497661, 2015). "Curcumin has been shown to attenuate colitis in the dinitrobenzenesulfonic acid (DNB)-induced murine model of colitis with a reduction in MPO activity, IL-1β expression, and reduction of p38 MAPK." (PMID 26007179, 2015). "Treatment with 2% DSS induced colitis, the severity of which was assessed by animal weight, colon length, colon weight, and colonic MPO levels." (PMID 25414650, 2014). "Our study demonstrates that apocynin treatment resulted in a marked improvement of the damage score and lower MPO activity in TNFα-induced colitis." (PMID 25276054, 2014). "AM841 (0.1 mg/kg, i.p., once daily 15 min before and for 3 days after induction of colitis) significantly attenuated intestinal inflammation, as shown by a reduction of macroscopic score and MPO activity." (PMID 25275313, 2014). "We also found that the reducing tendency of MPO after CK and BBR treatment in colitis mice plasma was the same as the colon MPO activity." (PMID 24504372, 2014). "On day five following colitis induction, animals were euthanized and distal colons were assessed macroscopically, histologically, and biochemically (assessment of myeloperoxidase activity)." (PMID 27355055, 2014). "Histological analysis revealed more severe colitis in PPARγVillinCre+ mice than in PPARγVillinCre- mice, with significantly increased neutrophil infiltration and MPO activity." (PMID 24465207, 2014). "Our results demonstrate that, during DSS-induced colitis in mice, MPO activity and F4/80 cell numbers were significantly increased, and ATIC treatment markedly attenuated these responses." (PMID 25051185, 2014).
colitis (continued). "Intrarectal administration of XLS attenuated the DSS-induced colitis, as evidenced by a reduction in both the histological damage score and myeloperoxidase activity." (PMID 25120575, 2014). "A histological damage score and the activity of tissue myeloperoxidase were used to evaluate the severity of the colitis." (PMID 25120575, 2014). "In the current work we assessed the severity of colitis via an increase in colonic MPO content, colon weight and circulating IL-6 and IL-18 levels as well as by a decrease in colon length and body weight." (PMID 25414650, 2014). "Meanwhile, 20 mg/kg CK and 100 mg/kg BBR treatment reduced the MPO by 705.3±11.27 mU/g (p<0.001) and 558.3±30.71 mU/g (p<0.001) in severe colitis mice compared to the model group, respectively." (PMID 24504372, 2014). "As compared to untreated colitis mice, the levels of MPO positive neutrophils and Mac-1 positive cells, which include macrophages, NK cells and granulocytes were significantly reduced in the colon following ERCs treatment (*p < 0.05)." (PMID 25475342, 2014). "TNFα-induced colitis was characterized by a substantial neutrophil infiltration, as shown by the presence of MPO activity in the inflamed colon." (PMID 25276054, 2014). "Colitis also significantly increased the colonoscopic, macroscopic and microscopic scores and the MPO activity." (PMID 25313594, 2014). "After treatment with Medilac-S, the activities of SOD were significantly increased (P < 0.01) and the activities of MPO were decreased (P < 0.01) in experimental colitis rats." (PMID 25276470, 2014). "TNBS-induced colitis mimics human IBD with respect to several histological alterations including mucosal invasion of PMN cells as indicated by MPO which also generates hypochlorous acid and contributes to colon injury." (PMID 24831514, 2014). "In the sedentary colitis group on average, 50% of the 8 cm colonic portion was inflamed with ulceration and we have also found a 30-fold elevation in MPO activity." (PMID 24683438, 2014). "Colonic MPO expression and activity were elevated in Eng+/+ mice throughout colitis but decreased with time in DSS-treated Eng+/− mice." (PMID 25114380, 2014). "Consistent with the Ly-6B staining, quantification of MPO concentration (an indicator for neutrophil influx) in the colon showed that DSS treatment significantly increased the MPO concentration in colon of colitis mice." (PMID 24787575, 2014). "The MPO activity was higher in the animals treated with propolis than in the animals with untreated colitis at 14 days." (PMID 24101941, 2013). "In the rat model, AA-induced colitis was accompanied by an increase in MPO activity by 14.4 or 5.36 times." (PMID 24001404, 2013). "There was a 7-fold increase in MPO activity in the colon in mice with DSS-induced colitis on the 8th day of the experiment." (PMID 23469045, 2013). "Severity of colitis was evaluated by colon histomorphology measurements, histopathology scores, tissue myeloperoxidase activity, as well as concentrations of malondialdehyde and pro-inflammatory mediators in the plasma and colon." (PMID 24001404, 2013). "The leukocyte infiltration into the mucosa and submucosa of the small intestine of mice with colitis at 6 DPI was associated with increased concentration of IL-6, IL-12p70, IL-10, IL-22 MCP-1 and TNF-α, IL-1β, MPO but lower concentration of IL-17A." (PMID 24167594, 2013). "Sinomenine (100 or 200 mg/kg)-treated mice with TNBS-induced colitis were significantly improved in terms of body weight, survival rate, diarrhea score, histological score and MPO activity compared with untreated mice." (PMID 24066068, 2013). "The MPO data indicate that EE promotes DSS-induced colitis by enhancing leukocyte infiltration in the colonic tissue." (PMID 23349972, 2013). "As judged from the increase in tissue MPO levels, the degree of gastric inflammation appeared to be lower than the degree of colonic inflammation." (PMID 23349972, 2013).
colitis (continued). "TNBS colitis also increases MPO activity in the colonic mucosa, an index of neutrophil infiltration." (PMID 23166707, 2012). "The disease activity index (DAI) score and MPO activity in the colonic mucosa were significantly decreased by treatment with CORM-2 in an acute mouse colitis model induced by DSS." (PMID 22943587, 2012). "The MPO activity in the colonic mucosa after the induction of colitis with TNBS was significantly inhibited by treatment with colonic CO gas insufflation." (PMID 22943587, 2012). "Substantial PMN recruitment into the colonic tissue was further confirmed by the increased MPO activity in DSS-induced colitis." (PMID 23209802, 2012). "In contrast, MPO activity in the colonic mucosa was markedly increased in animals with TNBS-induced colitis relative to that of the sham-operated group." (PMID 22943587, 2012). "L-Arg supplementation improved the clinical parameters of survival, body weight loss, and colon weight, and reduced colonic permeability and the number of myeloperoxidase-positive neutrophils in DSS colitis." (PMID 22428068, 2012). "DSS-induced colitis led to a significant increase in MPO activity in the colon, an effect which was largely prevented by pretreatment with either STW 5 or sulfasalazine (p < 0.001)." (PMID 22562255, 2012). "The unconjugated parent TLR7 ligand (1V136) reduced MPO-positive cell infiltration in DSS-colitis, indicating that 1V136 treatments attenuated neutrophil recruitment into the colon." (PMID 22619481, 2012). "The oral treatment by FSG significantly reduced TNBS-induced increase in colonic MPO activity at all time points after induction of colitis (p<0.05)." (PMID 23166707, 2012). "Neutrophil infiltration is usually associated with increased MPO activity, a parameter which correlates well with the severity of the lesions in acute DSS-induced colitis." (PMID 22562255, 2012). "The increased MPO activity in mice with DSS-induced colitis was significantly reduced after administration of picroliv." (PMID 23125487, 2012). "This rise in MPO activity during later stages of DSS-induced colitis were further corroborated by the alteration in the gene expression of CINC-1, an analogue of human IL-8 and a rat chemokine that has potent chemo attractant effects on neutrophils." (PMID 21949848, 2011). "The myeloperoxidase (MPO) assay is a well-accepted tool to measure tissue inflammatory damage in animal models of colitis." (PMID 22220274, 2011). "BTZO-15 significantly decreased the ulcer-affected area with suppression of rectal MPO activity in rats with TNBS-induced colitis." (PMID 21853095, 2011). "At day 14, DSS-treated animals also exhibited severe colitis in the distal colon, as measured by a significant increase in MPO activity compared to control animals." (PMID 22220274, 2011). "Large intestine shortening, rectum weight gain, diarrhea, intestinal bleeding, and an increase in rectal myeloperoxidase (MPO) activity were observed in a dextran sulfate sodium (DSS)-induced colitis rat model." (PMID 21853095, 2011). "Subsequently, we investigated the function of neutrophilic granulocyte using myeloperoxidase (MPO) assay; in addition, the severity of colitis was also assessed by both macroscopical and histological detection." (PMID 21785630, 2011). "Here, DSS-mediated colitis induces MPO activity and relevantly treatment with euphol prevented the increase in MPO activity." (PMID 22073270, 2011). "This treatment attenuated colitis development as evaluated by assessing body weight changes, the macroscopic damage score and the MPO activity (n = 8-10." (PMID 21829567, 2011). "Neutrophils are required for recovery from C. rodentium-induced colitis with both recruitment and MPO production peaking at 2 WPI." (PMID 20976045, 2010). "Additional markers of colitis included in vitro colonic permeability at 8 weeks of age, and at 17 weeks of age, colonic cytokine secretion, MPO content and histology." (PMID 18829978, 2009).
colitis (continued). "We found that tissue MPO activity as an index of neutrophil infiltration significantly reduced in all groups compare to the colitis control." (PMID 17069659, 2006). "Colonic myeloperoxidase activity decreased significantly in all groups compared to the colitis control group." (PMID 17069659, 2006). "Samples were collected 7 days after colitis induction, for intestinal bacterial flora, bacterial translocation, short chain fatty acids (SCFAs), myeloperoxidase (MPO), cytokines (IL-1β, TNF-α, IL-10 and TGF-β) and malondialdehyde (MDA)." (PMID 17069659, 2006). "In the bet3+colitis group, oxidant parameters such as malondialdehyde and myeloperoxidase and antioxidant parameters such as SOD inhibition rate were found to be higher than in the control group, while antioxidant enzyme activity values such as catalase were found to be lower (p < 0.001)." (PMID 41515203, 2025). "Furthermore, in an experimental colitis model, cycloartenyl ferulate attenuated both the clinical signs and symptoms of the disease and inhibited MPO activity." (PMID 40559438, 2025). "What's more, according to the IF-stained sections of colonic tissues, EcN@TeL could normalize the MPO expression, evidencing that EcN@TeL could effectively prevent the impending oxidative damage attributed to colitis." (PMID 40487164, 2025). "To address this issue, we examined immune cell populations in colitis-sensitive and colitis-resistant mouse models by immunohistochemistry (IHC) staining of myeloperoxidase (MPO; for neutrophils), CD68 (for macrophages/monocytes), CD4, and CD8 on colon sections from different mouse strains." (PMID 40749055, 2025). "The DSS-induced colitis model effectively replicates several key pathological features of UC, including significant weight loss, diarrhea, hematochezia, and the elevation of markers such as DAI and MPO, which are indicative of inflammation." (PMID 41196878, 2025). "In addition to DAI scores, our study found a significant increase in MPO activity in the colitis group, which is an indicator of inflammation." (PMID 40255550, 2025). "In an animal study, treatment with apigenin-Mn(II)-loaded hyaluronic acid nanoparticles significantly improved colitis, significantly decreased MPO activity, inflammatory cytokine secretion, and oxidative injury, and had no side effects in mice with DSS-induced colitis." (PMID 39451206, 2024). "The synergistic effects of BITC and RES on DSS-induced colitis were subsequently assessed by evaluating myeloperoxidase (MPO) and inducible nitric oxide synthase (iNOS) levels; the levels of inflammatory factors, including IL-10, TNF-α, IL-1β and IL-6; and changes in the colon flora." (PMID 38998586, 2024). "Herein, we examined the impact of genetic manipulation of MPO to study its role in a widely employed murine model of experimental colitis and attempted to describe the possible mechanisms that interplay with MPO-deficiency and the immune response during inflammation." (PMID 38673843, 2024). "Furthermore, ZW3 significantly reduced neutrophil number/HPF and colonic myeloperoxidase (MPO) activity in colitis mice (p < 0.05)." (PMID 38203732, 2024). "Lastly, end-point indicators of colitis severity were increased in MPO KO DSS mice (p ≤ 0.001) compared with Wt-DSS mice, and both groups recorded significantly increased spleen weight to bodyweight ratios (p ≤ 0.001 and p < 0.5, respectively) relative to their control counterparts." (PMID 38673843, 2024). "Both fresh feces and heat-inactivated feces could alleviate DAI, the increased content of colonic MPO and EPO, impairment of colonic morphology and histological index of colitis caused by DSS treatment." (PMID 39347394, 2024). "The regulatory effect of LP-HFY11 on the levels of MPO, NO, GSH, and MDA in mouse colon tissue may also be an essential mechanism underlying its alleviating effect on mouse colitis." (PMID 38790796, 2024).